C3 (complement C3)
Diseases named in the same sentence as C3 in open-access papers (continued):
Sharing a sentence is not in itself a finding about the gene and the disease.
lupus (continued). "In this patient, hypoalbuminemia, decreased C3, increased CRP, and high SLEDAI implied an increase in lupus activity, but the significant association between these findings and the occurrence of severe hyponatremia was inconclusive." (PMID 34596163, 2021). "In a longitudinal studies of pediatric lupus patients, it was found that patients with chronic hypertension persistently presented with higher serum protein levels of complement C4 and C3, and higher gene copy number of C4B." (PMID 34764957, 2021). "The C3 deposits in the glomeruli were decreased in the ADSC group compared to the lupus group and were the lowest in the miR-20a group (all P < 0.05)." (PMID 34721589, 2021). "The preterm birth group had lower serum C3 levels than the full-term birth group before pregnancy, which indicated that a pre-pregnancy serum C3 level < 85 mg/dl and a history of lupus nephritis are potential risk factors for preterm birth in pregnancies with SLE." (PMID 33980284, 2021). "In a European multinational inception cohort of 200 newly diagnosed (within two years) lupus patients, many of whom had active disease, low C3 and/or C4 levels were observed at baseline in 54%." (PMID 33569681, 2021). "Decreased complement 3 (C3) is a widely used biomarker for active disease in systemic lupus erythematosus (SLE)." (PMID 33627173, 2021). "In the current study, there was a relatively high level of C3/IgG deposits in the glomeruli, and further research showed that podocyte injury occurs in the lupus group, and ADSC/miR-20a-ADSC treatment prevents podocyte damage." (PMID 34721589, 2021). "Detection of complement components (C1q, C3, and C4) and immunoglobulins (Ig) at the dermo-epidermal junction (the so-called lupus band) has been used in CLE diagnostics in many decades using the direct immunofluorescence technique." (PMID 33931094, 2021). "The role of the complement cascade in LN is well evidenced; deficiencies in components of the complement cascade can lead to monogenic lupus (C1q, C2 and C4) and low levels of C3 and C4 are assessed in the clinic to monitor disease activity." (PMID 32605540, 2020). "Since the deposition of IC is an important characteristic of lupus, IgG-IC and C3-IC levels in the glomeruli were analyzed using immunofluorescence staining." (PMID 32462028, 2020). "Li H. and his colleagues measured complement levels C3 and C4 in Chinese patients with systemic lupus erythematosus (SLE)." (PMID 33193314, 2020). "More than 64% of children had presentation of the lupus-related markers, such as positive ds-DNA, low level of serum C3 or C4, and increased ESR." (PMID 31036039, 2019). "In systemic lupus erythematosus, a low CR1 density on neutrophils and other phagocytes causes excessive C3 activation, the release of proinflammatory cytokines, and immune-complex overload." (PMID 31824479, 2019). "Around half the patients with systemic lupus erythematosus (SLE) have low C3 and C4 complement concentrations." (PMID 31200658, 2019). "RA LNSCs specific enrichment involved pathways like Systemic lupus erythematosus (e.g., C3), cytokine signaling (e.g., IL-7) and packaging of telomere ends (e.g., histone cluster genes)." (PMID 31481955, 2019). "Activation of miR-654 reduced IL-1β, IL-6, IL-8, and TNF-α production, reduced gomerulonephritis, and decreased MIF, IgG, and C3 expression in murine lupus glomeruli." (PMID 31608058, 2019). "Among specific tests, determination of ANA, C3, C4 and the antibodies against ds-DNA, cardiolipin and β2-Glycoprotein, as well as lupus anticoagulans are to be recommended." (PMID 33324879, 2019). "Deficiency of the AP components in lupus-prone MRL/lpr mice, such as FB and FD, exhibited significantly decreased glomerular C3 deposition levels, maintained serum C3 levels, and improved glomerular pathological score." (PMID 29892304, 2018). "Increased CTSL-mediated C3 activation, on the other hand, drives Th1 hyper-activity in rheumatoid arthritis and in systemic lupus erythematosus." (PMID 30405635, 2018).
lupus (continued). "Typical linear or granular deposits of immunoglobulins (IgG and IgM) and C3 at the dermoepidermal junction can be seen and are sufficient to constitute a positive lupus band test." (PMID 28143420, 2017). "Low serum levels of complement components C3 and C4 have been used for over 50 years to indicate lupus activity and are included in the Systemic Lupus Erythematosus Disease Activity Index (SLEDAI)." (PMID 29208014, 2017). "Accordingly, B7-H4-KO-BMDCs-ALD-DNA induced lupus mice displayed more splenomegaly and lymphadenopathy, as well as kidney lesions with the deposition of immunoglobulin and complement C3." (PMID 29321778, 2017). "WML were repeatedly correlated with lupus duration, cognitive dysfunction, cerebrovascular syndrome, seizures, antiphospholipid antibody and low complement (C3, C4, CH50) levels." (PMID 27570507, 2016). "Each patient's lupus activity was determined by serological tests including antidouble-stranded DNA antibody (anti-dsDNA), complement levels (C3, C4), erythrocyte sedimentation rate (ESR), and antinuclear antibody (ANA)." (PMID 27428227, 2016). "In other words, low C3 and C4 are both important indicators for lupus activity due to their involvements in classical and alternative complement pathways, but C4 is less capable of monitoring lupus activity." (PMID 27428227, 2016). "In lupus, immune complexes formed by IgG and IgM autoantibodies and self-antigens activate complement lowering both C3 and C4 levels." (PMID 26583157, 2015). "These pilot experiments confirm that radiolabeled C3 probes can detect glomerular C3 fragments in mice with lupus-like glomerulonephritis." (PMID 26309728, 2015). "Anti-CRP-Ab levels were studied in relation to routine laboratory tests, urine analysis, levels of C3, C4, other immunological markers and the overall disease activity as assessed by Systemic Lupus Erythematosus Disease Activity Index (SLEDAI)." (PMID 26704903, 2015). "Lupus patients usually have low C3 and C4 levels during disease flares because of activation of the complement system by immune complexes (ICs)." (PMID 25886501, 2015). "This was proven when the C57BL/6-PDCD1−/− mice presented with autoimmune features resembling to SLE, e.g., lupus-like glomerulonephritis with the deposition of IgG3 and C3, arthritis and splenomegaly." (PMID 25938972, 2015). "As a result of this activation, patients with active lupus present hypocomplementemia during disease flares, but C3 and C4 levels are recovered between episodes." (PMID 25886501, 2015). "Herein, we demonstrated that total dsDNA antibodies measured by a routine indirect ELISA can present a correlation with lupus activity and C3 levels." (PMID 26583157, 2015). "We did not detect any association with the commonly used serological markers of active lupus (elevated anti-dsDNA and low C3) or with persistent overall disease activity for either NN or NA." (PMID 24502558, 2014). "Low C4 and C3 in the presence of anti-double-stranded antibodies have nearly a 100% specificity for lupus." (PMID 23737826, 2013). "The performance of TWEAK as a biomarker for nephritis was compared with routinely used laboratory tests in lupus patients, including anti-double stranded DNA antibodies and levels of C3 and C4." (PMID 19785730, 2009). "The lupus model showed significantly increased glomerular IgM, IgG, and C3 expressions." (PMID 40651955, 2025). "Similarly, data from clinical trials investigating TCZ in patients with systemic lupus erythematosus (SLE) have shown continued reductions in C3 and C4 levels despite clinical improvement." (PMID 40948753, 2025). "Patients with systemic lupus erythematosus showed higher levels of GDF5 compared to healthy controls, positively correlated with hematuria and disease activity, and was inversely associated with C3 and C4." (PMID 41303556, 2025).
lupus (continued). "The presence of a skin rash, leukopenia, hemolytic anemia, proteinuria, blood ANA 1:1280 positive, anti-dsDNA 1:1000 positive, poor complement (C3 and C4), and serositis (recurrent pericardial effusion) matches the 2019 EULAR/ACR diagnostic criteria for systemic lupus erythematosus." (PMID 39354993, 2024). "Additionally, our matching process, which took into account factors such as age, sex, lupus activity parameters (anti-dsDNA IgG titers and C3 levels), and organ damage (chronic kidney disease), helped mitigate the risk of selection bias." (PMID 39388388, 2024). "Indeed, the AUC value of TB Ag-NL was superior to C4 and ANA, and was almost close to the values of anti-dsDNA and C3, which were commonly used to determine the activity of lupus." (PMID 39090639, 2024). "C1q was more consumed in proliferative lupus, and correlated with anti-ds DNA, C3, and C4." (PMID 38586116, 2024). "Important lupus-related indices such as anti-dsDNA, C3, C4 values in para-clinic, and clinical disease manifestations including hematologic, musculoskeletal, kidney, cardiac, and central nervous system involvement compared in patients with and without periodontitis." (PMID 37941865, 2023). "To understand whether renal tubule changes associate with lupus disease progression, we performed immunostaining of CFB and C3." (PMID 37047136, 2023). "The pristane-induced lupus mice had different degrees of renal injuries, manifested as increased urine protein levels and more IgG and C3 deposition in the glomeruli of the mice receiving fecal microbiota from MRL/lpr mice compared with the FMT-Mpj mice and FMT-PBS mice." (PMID 36927795, 2023). "An increase in iC3b and other C3 fragments may contribute to complement-driven immune activation in diseases such as systemic lupus erythematosus (SLE) where patients have reduced levels of CR1 in erythrocytes." (PMID 35517827, 2022). "To date, the only other study—to the knowledge of the authors—to evaluate the complement cascade in pediatrics shows a profound effect of C1Q, C3, and C4 in pediatric subjects with systemic lupus erythematosus, which, notably, is tied to autoimmune activity and headache symptoms." (PMID 36670596, 2022). "In addition to IgG, IgM and C3 were deposited in a granular or shaggy pattern, known as a lupus band." (PMID 35990645, 2022). "Finally, treatment of lupus-prone mice with a soluble C3 inhibitor prevented the development of renal failure, albuminuria, and significantly reduced glomerulosclerosis." (PMID 33562189, 2021). "Moreover, some defects of complement pathway gene products, including C2, C3, C4 and C1q, play an important role in the pathogenesis of lupus." (PMID 34150746, 2021). "In addition, SLE patients with a history of lupus nephritis have an increased risk of preterm birth and may require strict control of disease activity based on serum C3 levels." (PMID 33980284, 2021). "Moreover, urine C3d showed a stronger correlation with the Systemic Lupus Erythematosus Disease Activity Index (SLEDAI) than serum C3, C3d, C4, or anti-dsDNA antibodies." (PMID 34281193, 2021). "Similarly, treatment of lupus-prone mice with a soluble CRIg-Fc increased serum C3 levels and significantly improved proteinuria and renal pathology, including a decrease in glomerular IC staining." (PMID 33562189, 2021). "However, the determination of C3/C4 and anti-dsDNA concentrations during pregnancy is useful for monitoring lupus activity." (PMID 37362416, 2021). "Similarly, the deposition of immunoglobulin and complement C3 in kidney lesions was more pronounced in HSD lupus mice than in NSD mice." (PMID 32296043, 2020). "Blocking P-selectin with mAb alleviated renal tubulointerstitial fibrosis, renal hypoxia, and peritubular capillary loss, without alteration of the levels of lupus activity indicators, anti-dsDNA antibody, or complement C3." (PMID 32138730, 2020).
lupus (continued). "Earlier notions on C levels refer to lupus pregnancies, which has become a topic of particular interest following the observation of an association between serum C3 and C4 levels and disease flares in non-gravid patients." (PMID 32973817, 2020). "Our findings suggest that blocking P-selectin with mAb alleviates renal tubulointerstitial fibrosis, renal hypoxia, and PTC loss without alteration of the levels of lupus activity indicators, anti-dsDNA antibody, or complement C3." (PMID 32138730, 2020). "Although recently study showed that C3 blocker effectively improved proteinuria and preserved renal function in lupus mice, despite its targeting earlier phases in the complement activation, potentency of C3 blocker to broadly suppress complement activation still raised similar concerns." (PMID 31752725, 2019). "During pregnancy, serum titers of C3 and C4 are usually elevated, so pregnant women with lupus flare might have normal levels of C3 and C4." (PMID 26295404, 2015). "However, these traditional biomarkers are not always appropriate for clinical monitoring, because high levels of anti-dsDNA or low levels of C3/C4 are persistent in some patients with lupus." (PMID 26608564, 2015). "Increased circulating anti-dsDNA antibodies and decreased C3 level predicted higher lupus activity." (PMID 24465439, 2014). "Furthermore, acquired conditions (e.g. systemic lupus erythematosus and glomerulonephritis due to C3 nephritic factor) that decrease the levels of circulating C3 increase the risk for invasive meningococcal disease by around 100-fold." (PMID 19388162, 2008). "In SLE, decreased levels of C3 and C4 have become classical indicators of disease activity, particularly reflecting activity and prognosis in lupus nephritis." (PMID 41187099, 2025). "Decreased serum C3 levels may result from congenital deficiency or secondary consumption due to autoimmune, infectious, or inflammatory diseases such as systemic lupus erythematosus (SLE), glomerulonephritis, post-streptococcal glomerulonephritis (APSGN), and infective endocarditis." (PMID 40995257, 2025). "For example, in systemic lupus erythematosus (SLE) with vasculitis, the levels of serum complement (C3, C4) were reduced, with complement levels being known to be lowered in SLE." (PMID 39456143, 2024). "Moreover, transfer of ILC3s also significantly increased the typical immune complex deposition of IgG and complement C3 in glomeruli compared to control lupus mice receiving PBS, as immunofluorescent staining revealed evidently raised fluorescence intensities of both IgG and C3." (PMID 37915129, 2023). "Low serum C3 levels and high SLEDAI-2K scores were reported as independent risk factors for the development of lupus myocarditis in patients with SLE." (PMID 36830735, 2023). "Additionally, the protein markers we selected could add more benefit to conventional biomarkers, such as C3, C4, and anti-dsDNA Ab, in predicting active lupus." (PMID 35966818, 2022). "For example, circIBTK expression is negatively correlated with the Systemic Lupus Erythematosus Disease Activity Index (SLEDAI) score as well as the levels of complement C3 and anti‐dsDNA in patients with SLE." (PMID 35770323, 2022). "SERPING1, C3, FGA, FGG, and CFH were significantly related to autoimmune diseases, and C3 in particular is associated with systemic lupus erythematosus (SLE) that shows a similar immunopathogenic basis to pSS." (PMID 34516718, 2021). "In lupus-prone mice, targeted reduction in circulating complement fB using antisense oligonucleotides prevented the development of hypocomplementemia, as well as LN-like pathology with reductions in proteinuria and glomerular C3 deposition and improved survival." (PMID 33562189, 2021). "The present study showed that management focusing on the history of lupus nephritis in addition to serum C3 levels in preconception care is important for predicting and preventing preterm birth in women with SLE." (PMID 33980284, 2021).
lupus (continued). "In addition, C1q deficiency, but not C3 deficiency, has been shown in mice to be associated with systemic lupus erythematosus—a disease caused by defective clearance of dead and dying cells." (PMID 34944007, 2021). "Finally, the percentages of CD161+ iNKT cells, perforin and granzyme B expression of expanded iNKT cells correlated with complement C3 levels, thus may confer protection against lupus flare." (PMID 34936686, 2021). "In addition, lupus IgG1-injected MRL-lpr/lpr mice exhibited significantly higher serum C3 and complement factors B and H levels, as well as significantly lower serum IFN-γ, IL-6, and IL-17 levels at 19 weeks of age, compared with those of control IgG1-treated and non-treated groups." (PMID 32625200, 2020). "Acquired complement deficiency can occur in the setting of autoimmune syndromes, such as systemic lupus erythematosus (SLE), with very low or, occasionally, undetectable C3 levels." (PMID 32972440, 2020). "Pregnant women with lupus nephritis display significantly lower levels of C3 and C4 more often than other SLE subjects." (PMID 32973817, 2020). "Statistical analysis was conducted to assess the efficacy (proteinuria, systemic lupus erythematosus disease activity index (SLEDAI), Scr, BUN, albumin, C3, and C4) and safety (rate of adverse events) of MSCs for SLE using Cochrane Review Manager Version 5.3." (PMID 32322279, 2020). "Both low C3 and C4 are biomarkers of disease activity and were recently included as immunologic criteria for SLE by the Systemic Lupus International Collaborating Clinics (SLICC) group." (PMID 26583157, 2015). "Anti-RG antibody titer actually increased in coincidence with RG blooms and lupus flares and correlated directly with SLEDAI and anti-DNA levels and inversely with C3 and C4." (PMID 40005809, 2025). "The mean systemic lupus erythematosus disease activity index (SLEDAI) score was 14.6 ± 4.4, and 95% of patients had complement C3 consumption (mean C3 57.2 ± 22.6 mg/dL)." (PMID 41515921, 2025). "The levels of IFI44 positively correlate with serum creatinine and the Systemic Lupus Erythematosus Disease Activity Index (SLEDAI) and inversely with serum complement C3 and initial estimated glomerular filtration rate (eGFR)." (PMID 40101924, 2025). "Other kidney conditions may also have IgA deposits, especially systemic lupus erythematosus (SLE)-associated nephritis, but this can usually be distinguished by the typical so-called “full-house” positive immunofluorescence staining for IgG, IgA, IgM, C1q, and C3 in SLE." (PMID 38438966, 2024). "Subjects with anxiety and depression were assessed for disease activity using the Mexican Systemic Lupus Erythematosus Systemic Disease Activity (Mex-SLEDAI), and blood samples were collected to test complement C3 and C4 levels." (PMID 37884917, 2023). "The measurement of serum C3 and C4 levels has been used to assess SLE disease activity using the Systemic Lupus Erythematosus Disease Activity Index (SLEDAI)." (PMID 38186533, 2023). "Because there are other causes of low C3 levels in nephritis, such as C3 glomerulopathy and systemic lupus erythematosus, all cases of APSGN should have normalization of their C3 level 8–12 weeks after symptom onset." (PMID 36128411, 2022). "There were some differences in Systemic Lupus Erythematosus Disease Activity Index (SLEDAI), Creatinine (Cr), Blood Urea Nitrogen (BUN), C3, C4, and Albumin (Alb) among various ISN/RPS class LN patients." (PMID 35572531, 2022). "The results also showed that TGP contributed to a betterment in improving other outcomes related to lupus activity, such as ESR, CRP, complement proteins (C3, C4), and immunoglobulins (IgA, IgM)." (PMID 35173622, 2022). "For instance, this group of patients showed lower Systemic Lupus Erythematosus Disease Activity Index (SLEDAI), lupus activity index (LAI), and renal and hematologic activity; higher C3 and C4; and low use of prednisone." (PMID 36040804, 2022).